YAP1 (Yes1 associated transcriptional regulator)
Diseases named in the same sentence as YAP1 in open-access papers (continued):
Sharing a sentence is not in itself a finding about the gene and the disease.
tumor (continued). "Mechanistically, this effect was mediated through the activation of Yes-associated protein 1 (YAP1), which transcriptionally upregulates LOX expression and secretion from tumor cells." (PMID 38254796, 2024). "In particular, FAT4 silencing in ALCL cells activated the β-catenin and YAP1 pathways, which play crucial roles in tumor growth, and conferred resistance to chemotherapy." (PMID 39478125, 2024). "We discovered that the highly expressed transcriptional coregulator Yap1 promotes the deposition of a pro-tumor matrix protein, ColVI, in the UPS ECM." (PMID 38652549, 2024). "In vivo studies also confirmed that GL-V9 exerts anti-tumor effects by suppressing YAP1 expression, while also activating autophagy and inducing mitochondrial apoptosis in BXPC-3-bearing BALB/c nude mice." (PMID 39458993, 2024). "The work we present situates the HIPPO/YAP1 axis as a signaling cascade downstream of STK11 that modulates tumor-intrinsic cytokine expression." (PMID 37968341, 2024). "Taken together, our data reveal that YAP1 acts as a downstream effector of the ZBTB11-PRRG2 regulatory axis to modulate tumor metastasis." (PMID 38355937, 2024). "The Hippo signaling components LATS1/2, each encoding a tumor-suppressive serine or threonine-protein kinase, phosphorylate their effectors TAZ/YAP, causing YAP1 and TAZ’s cytoplasmic retention and destabilization." (PMID 39531326, 2024). "Promote LAST1 phosphorylation and inhibits YAP1 expression in HCC cells, resulting in YAP1 phosphorylation and reduced nuclear translocation; Induce apoptosis, inhibit tumor cell migration, invasion and epithelial-to-mesenchymal cell transition through YAP1." (PMID 38550587, 2024). "As expected, pharmacological inhibition of YAP1 in combination with anti–PD-L1 antibody showed significant tumor growth inhibition compared with any single therapy." (PMID 39630608, 2024). "Collectively, these observations confirm that the transcriptional changes observed in our RNAseq profiling of Gp130FF; Yap1KO tumors arises as a direct consequence of reduced epithelial Yap1 expression we observe in Yap1KD; Gp130FF tumor organoids." (PMID 37957015, 2024). "FAT1 has been reported to reduce nuclear localization of Yes1 associated transcriptional regulator (YAP1) by maintaining Hippo pathway activity, thereby inhibiting tumor proliferation." (PMID 38782965, 2024). "YAP1 also possesses mechanosensory functions, and its nuclear localization and activity increase in response to stiff environments such as those in tumor tissue." (PMID 38652549, 2024). "As a tumor-promoting factor, YAP1 activation induced by hypoxia is the key to promoting glycolysis of HCC cells." (PMID 38550587, 2024). "Further investigation revealed that lactate derived from CAFs negatively regulates the HIPPO pathway through the DLG5/CUL3/MST1 axis, thus promoting the nuclear localization of YAP1 and enhancing the tumor stem cell phenotype." (PMID 39605072, 2024). "Our findings demonstrate that, in contrast to SCLC, both xenografts of SMARCA4-mutant cell lines previously classified as SCLC-Y and patient-derived primary SMARCA4-UT tumor samples show diffuse, uniformly strong YAP1 protein staining." (PMID 38180245, 2024). "YAP1 exerts its tumor-promoting role partly by regulating autophagy in Osimertinib resistant NSCLC cells." (PMID 37215986, 2023). "Here we report that selective ablation of stearoyl CoA desaturase-2 (Scd2) in aHSC globally suppresses nuclear CTNNB1 and YAP1 in tumors and tumor microenvironment and prevents liver tumorigenesis in male mice." (PMID 37156770, 2023). "Both IL6ST and YAP1 have been shown to promote tumorigenic features of tumor cells, such as proliferation and migration." (PMID 35435804, 2023). "The oncoprotein YAP1 is targeted by miR-375 and can be inactivated via the Hippo tumor suppressor pathway." (PMID 38505381, 2023).
tumor (continued). "YAP1 inhibitor and erlotinib synergistically reduced migration, invasion, and tumor sphere formation of erlotinib-resistant NSCLC 17,22,23." (PMID 37215986, 2023). "Solute carrier family 39 member 4 (ZIP4) activates integrin α3 (ITGA3) by regulating the co-activation of ZEB1 and yes-associated protein 1 (YAP1) to promote EMT, tumor colonisation and organogenesis in vitro and vivo models of PC." (PMID 37550301, 2023). "In particular, the tumor growth rate, the number of tumor nodules, and the volume of ascites in Yap1−/− mice were approximately 4.5-fold greater than those in either WT or Yap1+/− mice." (PMID 36624516, 2023). "As the key downstream effector of Hippo signaling, our previous study has revealed that YAP1 regulated cancer stemness and tumor progression in TNBC cells." (PMID 36633714, 2023). "This is attributed to the role that YAP1 activation plays in affecting the tumor microenvironment, inducing resistance to chemotherapy, and performing as an intrinsic oncogenic driver." (PMID 37240355, 2023). "The Hippo pathway is an evolutionarily conserved tumor suppressor signal transduction pathway, and it ultimately inhibits tumor progression via YAP1/TAZ phosphorylation." (PMID 36823643, 2023). "Genetic or pharmacological inhibition of LTB4R2 recapitulates CTNNB1 and YAP1 inactivation and tumor suppression in culture and in vivo." (PMID 37156770, 2023). "This significant finding demonstrates how YAP1 can aid tumor cell escape even with targeted chemotherapy." (PMID 37444578, 2023). "The results showed that tumor formation was more prevalent in Yap1+/− and Yap1−/− mice than in WT mice." (PMID 36624516, 2023). "The tumor sample that showed YAP-1 overexpression in the normal adjacent epithelium was of a 29-year-old HIV+ female patient diagnosed with a well-differentiated invasive squamous carcinoma." (PMID 37476371, 2023). "Cells were also probed for YAP1 by IF and observed to express this tumor marker in cultured tumor cell nuclei as well." (PMID 37007076, 2023). "This study indicates that YAP1 promotes tumor vasculature formation and malignant progression in an m6A-dependent manner in vitro." (PMID 38053093, 2023). "Another mechanism by which tumor cells can survive and recur is K-Ras activation by YAP1, even after K-Ras inhibition." (PMID 37444578, 2023). "Our previous work has confirmed that YAP1 regulated the stemness and promoted the growth of tumor cells, and it was closely related to EGFR-TKI resistance." (PMID 37388902, 2023). "This is of particular importance because experiments in mice have shown that relapsed KRAS pancreatic tumours have activated YAP1/TEAD2 transcriptional programs that are required for tumour growth." (PMID 36175301, 2023). "STK38/STK38L kinases phosphorylate the transcriptional coactivator yes-associated protein (YAP1) and thereby negatively regulate YAP1 transcriptional activity, suggesting that STK38/STK38L function as tumor suppressors." (PMID 37046714, 2023). "Stromal-specific knockout (cKO) of Yap1 in murine models shaped the GROα-enriched microenvironment, facilitating in vivo tumor colonization, but this effect was reversed after Cxcr1/2 depletion in OvCa cells." (PMID 36624516, 2023). "During tumorigenesis driven by Apc/Kras, PCs share features with the Yap1-dependent revival stem cell identity, and further activate Tgf-β and Wnt signaling in their conversion to bona fide tumor cells." (PMID 36711533, 2023). "YAP1, a multifunctional intracellular connexin, and transcription coactivator plays a central hub in the Hippo signaling pathway and the proliferation of tumor cells." (PMID 37593048, 2023). "Taken together, these findings suggest that GROα in the CM of Yap1-depleted stroma is responsible for facilitating tumor colonization of OvCa cells, and GROα exerts a relatively stronger oncogenic potential to OvCa cells." (PMID 36624516, 2023).
tumor (continued). "In this study, we identified that lncRNA PVT1 regulates cancer stemness, metastasis, and anti-tumor immunity by controlling the DNA damage response and the miR-375/YAP1 axis." (PMID 36894542, 2023). "There is a question: does RNA methylation participate in regulating tumor angiogenesis through the Hippo/YAP1 pathway?" (PMID 38053093, 2023). "It was found that YAP1 overexpression partially reversed the tumor-inhibiting effect of TPM2 overexpression." (PMID 36823643, 2023). "By establishing SGC-7901 CSC models with circ_0051246, miR-375, and YAP1 knockdown or overexpression, and an orthotopic xenograft tumor model, we provide a new target for GC screening and treatment." (PMID 38505381, 2023). "YAP1 is a well-known oncoprotein in GC that can be inactivated via the Hippo tumor suppressor pathway." (PMID 38505381, 2023). "Increased expression of FGB has been associated with cancer metastasis and poor prognosis in various types of cancers, while YAP1 overexpression has been observed in multiple cancers, promoting tumor growth and metastasis." (PMID 37953225, 2023). "Of note, the concentration of GROα in the ascites of Yap1−/− mice was 2- to 3-fold greater than that of WT or Yap1+/− mice, suggesting that GROα is relatively dominant as a potential tumor-promoting chemokine." (PMID 36624516, 2023). "Functional assays also confirmed the oncogenic potential of GROα in the conditioned medium of Yap1 cKO stroma, suggesting that tumor-derived miR-141 remodels stromal cells to become CAFs, which secrete GROα to promote tumor colonization during OvCa metastasis." (PMID 36624516, 2023). "Specifically, the favorable prognosis of high-YAP1 tumor in incremental ESR1 expression supports the inhibitory role of YAP1 on ESR1 signaling." (PMID 37894401, 2023). "We also preliminarily investigated the changes in the tumor immune microenvironment after treatment with YAP1 inhibitor and chemoimmunotherapy." (PMID 37752152, 2023). "Subcutaneous tumor analysis revealed that overexpression of PDLIM7 significantly enhanced YAP1 staining abundance in the nucleus." (PMID 36823643, 2023). "The inhibition of YAP1 suppressed tumor growth in PDX models and blocked PM in PDO models, providing a strong rationale to target it in clinical settings." (PMID 37892663, 2023). "Our results also validate that CA3, in combination with osimertinib, executes its anti-metastasis and pro-tumor apoptosis partly through autophagy and the YAP1/DUSP1/EGFR/MEK/ERK regulatory feedback loop in osimertinib-resistant cells." (PMID 37215986, 2023). "The top pathway in the non-tumor-specific sex-DMPs of SHH is YAP1- and WWTR1 (TAZ)-stimulated gene expression." (PMID 37035203, 2023). "Here, we characterized the expression profiles of MCC tumor biopsies, PDCLs, and established cell lines to identify a spectrum of NE gene expression that is negatively correlated with the expression of YAP1 and WWTR1." (PMID 36719743, 2023). "The majority of research supports the classification of miR-375 and YAP1 as important tumor suppressors." (PMID 36894542, 2023). "Currently, numerous relevant studies indicate that Hippo/YAP1 pathway-related RNA methylation plays a regulatory role in tumor angiogenesis." (PMID 38053093, 2023). "YAP1–MAMLD1 gene fusion‐driven neuroepithelial tumours demonstrating hyperproliferation showed an increase in Yap1 expression, which correlated with an increase in Pax6." (PMID 36656098, 2023). "Ezrin and YAP1 are highly expressed in tumor cells, and Ezrin can regulate YAP1 expression, thereby promoting cancer occurrence and development." (PMID 37791063, 2023). "YAP1 is a key member of the Hippo signaling pathway and a transcriptional coactivator regulating tumor cell proliferation, cell cycle, survival, and differentiation in combination with TEAD and ultimately leading to the occurrence and progression of HCC." (PMID 36755690, 2023).
tumor (continued). "Here, we report that a cancer-secreted miRNA, miR-141, reprograms stromal cells to a tumor-promoting stromal niche via the miR-141/YAP1/GROα signaling cascade." (PMID 36624516, 2023). "Compared to PC-9/AR/vector and PC-9/AR/shYAP1 xenograft, tumor growth of YAP1 knocked down xenograft was significantly retarded." (PMID 37215986, 2023). "We found that FAT1 was significantly increased in Z8-treated xenografts in addition to the retention of YAP1 in the cytoplasm of tumor cells and suppression of ALDH1A1." (PMID 37147285, 2023). "Immunohistochemistry was used to assess YAP-1 protein overexpression in tumor tissue relative to surrounding benign squamous epithelium." (PMID 37476371, 2023). "An acidic tumor microenvironment, linked with a hypoxic environment, promotes the expression of malic enzyme 1 and brings EMT to tumor cells through YAP1 activation." (PMID 36982569, 2023). "At the same time, HIF can also be activated by PI3K/AKT, YAP/TAZ, hippo/YAP1 and other signaling pathways to further promote the glycolytic process of tumor cells." (PMID 37693915, 2023). "A statistically significant relation was observed between YAP1 expression and tumor size (P=0.003), tumor stage (P>0.001), tumor focality (P=0.037), lymph node metastasis (P=0.025) and extra-thyroidal extension (P=0.006)." (PMID 37383164, 2023). "YAP1 was reported as tumor suppressor in some studies, whereas it was correlated with poor prognosis in others." (PMID 37894401, 2023). "Herein, we used verteporfin, a small molecule inhibitor of YAP1, in combination with cisplatin-based chemotherapy to treat tumor-bearing mice." (PMID 38041044, 2023). "T‐DM1‐mediated HER‐2 inhibition increases ROR1 expression through YAP1 activation and confers drug resistance on tumor cells." (PMID 37799806, 2023). "Studies have reported that the PI3K pathway can be activated by signalings other than KRAS, and that amplification and the overexpression of the transcriptional coactivator Yap1 can also drive KRAS-independent PDAC tumor maintenance." (PMID 36675641, 2023). "The mobilization or upregulation of YAP1 can lead to tumor occurrence and resistance to chemotherapeutic drugs such as mitomycin C, cisplatin, and etoposide in GC." (PMID 37799806, 2023). "A statistically significant relation was observed between YAP1 expression and tumor size, tumor stage, tumor focality, lymph node metastases, and extrathyroidal extension (P-values were =0.003, > 0.001, 0.037, 0.025, and 0.006), respectively." (PMID 37383164, 2023). "The role of YAP1 in adaptive immune response was mostly studied in T‐cells of the tumor microenvironment." (PMID 37544916, 2023). "In this regard, the deletion of Taz and Yap1 in a mouse SCC model induced by Fat knockout decreased tumor stemness and metastasis." (PMID 37835395, 2023). "YAP1 profoundly modulates cell migration, tumor growth, and cancer stemness by complex mechanisms, such as the Hippo pathway, EMT pathway, epigenetic modification, and regulation of immune cell infiltration." (PMID 37752152, 2023). "We also observed that MT3 increased the expression of YAP1, potentially contributing to chemotherapy resistance by inducing tumor stemness through YAP1." (PMID 38041044, 2023). "The relevance of this mechanism is supported by the detection of high expression levels of YAP1 in the tumor stromal cells of PC patients with advanced tumor stage and poor prognosis." (PMID 37046676, 2023). "It is becoming increasingly evident that YAP1 is considered to promote tumor cell proliferation and inhibit apoptosis protein." (PMID 37593048, 2023). "Our studies describe how MUC13 facilitates metastasis after disseminating tumor cells from the primary tumor site by targeting YAP1 and influencing its nuclear translocation, followed by the activation/expression of pro-survival/metastasis-associated genes." (PMID 37793774, 2023).
tumor (continued). "A recent study found that interferon-γ induced tumor resistance to anti-PD-1 immunotherapy by promoting YAP1 phase separation." (PMID 37388902, 2023). "Higher expression of MUC13 and YAP1 was observed at different tumor stages compared with adjacent normal samples, highlighting the clinical significance of this novel molecular interaction." (PMID 37793774, 2023). "In GC cell models, this peptide reduces METTL3 expression, resulting in YAP1 downregulation and impairment of its tumor-promoting effects." (PMID 36635265, 2023). "YAP-1’s oncogenic role in the carcinogenesis of several human neoplasms has been studied and it has recently been found to drive SCC initiation and progression." (PMID 37476371, 2023). "MUC13 and YAP1 expression was significantly higher in the tumor area compared with the adjacent normal areas." (PMID 37793774, 2023). "YAP1 translocation to the nucleus upon Hippo pathway inactivation is an important tumor progression mechanism." (PMID 36936987, 2023). "YAP1 is a key step in the tumour-suppressive Hippo pathway, which controls cell proliferation, apoptosis, and organ size." (PMID 37870696, 2023). "STK4 is a key component in the Hippo pathway which functions as a tumor suppressor by phosphorylating and inactivating the YAP1 oncogene." (PMID 37745975, 2023). "Continuous efforts have been made to target KRAS, HIF1A, and YAP1 because of their roles in tumor initiation." (PMID 37990271, 2023). "Circ1662 was found to improve the efficiency of nuclear transport of YAP1 to downregulate SMAD3, causing the promotion of tumor aggressiveness." (PMID 36875073, 2023). "When it is overexpressed, circKRT17 recruites EIF4A3 to enhance YAP1 stabilization and nuclear import, upregulating osimertinib resistance in tumor cells." (PMID 37996892, 2023). "Together, these evidences highlight that YAP1 enhances immune evasion through inducing PD-L1 expression, remodeling the tumor immune microenvironment, and modulating immune-related signaling pathways." (PMID 37752152, 2023). "Three stable cell lines HCT116 Lv-anti-SNHG16 NC, HCT116 Lv-anti-SNHG16 + Lv-Oe-YAP1 NC, and HCT116 Lv-anti-SNHG16 + Lv-Oe-YAP1 were separately injected into the tail vein of mice to confirm the effect of SNHG16 on tumor metastasis." (PMID 36147462, 2022). "YAP1 is a transcriptional coactivator and involved in controlling normal tissue growth and tumor development." (PMID 36008392, 2022). "YAP1 is well known to promote cancer formation, tumor progression, and metastasis [41 but is less known to play a role in MSC-involved tumorigenicity." (PMID 35356283, 2022). "Here, we found both of the LIN28 and YAP1 protein levels were increased in CAL51-derived tumor spheres compared in CAL51 monolayer cells." (PMID 35102250, 2022). "YAP1 is known to correlate with expansion of cancer stem cells and tumor progression through interaction with cancer-promoting pathways, such as the NOTCH, and WNT pathways." (PMID 36045416, 2022). "Previous studies have indicated that YAP1 overexpression enhances tumor cell dissemination by promoting intravascular motility and re-entry into the systemic circulation." (PMID 35773411, 2022). "Abundant nuclear yes-associated protein 1 (YAP-1) is important for PSC activation and tumor-supporting paracrine signaling." (PMID 35884592, 2022). "In GC, there was a gradual increase of approximately three-fold in the ratio of YAP1-to-VGLL4 protein expression from GC grade I to grade IV, and their mRNA ratio was closely associated with aggressive tumor features." (PMID 36289774, 2022). "Our results showed, for the first time, that wogonin possesses anti-tumor effects and exhibits a new regulatory mechanism of YAP1 expression in CC cells." (PMID 35037825, 2022).